HK2 (hexokinase 2)
Diseases named in the same sentence as HK2 in open-access papers (continued):
Sharing a sentence is not in itself a finding about the gene and the disease.
breast tumor (14 papers, 2000 to 2025). "We showed that let-7b-5p suppresses not only aerobic glycolysis but also the growth and metastasis of breast tumors by inhibiting HK2-mediated glycolysis." (PMID 37019900, 2023). "By suppressing HK2-mediated aerobic glycolysis, let-7b-5p restrains breast tumor growth and metastasis both in vitro and in vivo." (PMID 37019900, 2023). "Let-7b-5p inhibits the growth and metastasis of breast tumours by inhibiting HK2-mediated aerobic glycolysis." (PMID 38052785, 2023). "The high expression of key glycolytic enzymes in breast tumour tissues, such as HK‐2 and enolase‐alpha, represents a marker for poor clinical outcome during TAM therapy." (PMID 34841716, 2021). "Research on the function of glycolysis-related genes in breast tumors showed that hexokinase (HK2) had high expression in breast IDC cells, and that HK2 silencing inhibited IDC." (PMID 33194424, 2020). "Importantly, let-7b-5p inhibitor-mediated enhancement of tumor growth was abrogated when HK2 was knocked down, revealing that let-7b-5p modulates breast tumor growth by HK2." (PMID 37019900, 2023). "Moreover, let-7b-5p inhibitor promoted lung metastasis of breast tumors, whereas HK2 knockdown blocked this effect." (PMID 37019900, 2023). "HK2 is overexpressed in a variety of tumor cells, and studies have shown that HK2 ablation delays lung and breast tumor progression, while HK2 silencing reinstates the flux of pyruvate to the TCA cycle and suppresses aerobic glycolysis, contributing to tumor therapy." (PMID 37892405, 2023). "Hence, breast tumors with overexpression of HK2, PFKM, and PKM2 may potentially be more malignant due to enhanced aerobic glycolysis." (PMID 35328104, 2022). "Of note, circKIF4A has been recently demonstrated to reprogram breast tumor glucose metabolism by sponging miR-335, which in turn modulates the expression of the OCT4/ALDOA (aldolase A)-HK2 (hexokinase 2)/PKM2 (pyruvate kinase M2) axis." (PMID 37627209, 2023). "As expected, the let-7b-5p inhibitor significantly enhanced the breast tumor growth of MDA-MB-231 cells, while HK2 knockdown dramatically resisted the growth." (PMID 37019900, 2023). "Our results showed highly significant overexpression of the crucial glycolytic genes (i.e., HK2, PFKM, and PKM2) in breast tumors as compared to their adjacent controls." (PMID 35328104, 2022). "Significant upregulation (p < 0.0001) of the glycolytic genes (HK2, PKM2, and PFKM) was observed in breast tumor tissues in comparison to their respective controls." (PMID 35328104, 2022). "Once a primary breast tumor was detected by palpation in experimental MMTV-PyMT; HK2f/f; UBC-CreERT2 mice and control MMTV-PyMT;HK2f/f mice, the mice were injected with tamoxifen for 7 consecutive days to systemically delete HK2 in the experimental MMTV-PyMT;HK2f/f;UBC-CreERT2 mice." (PMID 35173161, 2022).
gallbladder cancer (14 papers, 2019 to 2024). "In parallel, as a marker associated with gallbladder cancer, lncRNA PVT1 has been reported to induce invasion, metastasis and apoptosis resistance of gallbladder cancer cells by silencing HK2 via upregulation of miR-14326." (PMID 37859812, 2023). "For example, lncRNA PVT1 promotes tumor progression by regulating the miR-143/HK2 axis in gallbladder cancer." (PMID 35477447, 2022). "It is reported that the expression of lncRNA PVT1 is up-regulated in tumors, which regulates HK2 expression by competitively binding to endogenous miR-143 in gallbladder cancer cells and promotes aerobic glycolysis of tumor cells." (PMID 36292959, 2022). "PVT1 regulates the expression of HK2 in gallbladder cancer cells by competitive binding to miR-143, and controls aerobic glucose metabolism to promote cell proliferation and metastasis." (PMID 32153626, 2019). "Moreover, the PVT1/miR-143/HK2 axis promotes cell growth and metastasis by modulating aerobic glucose metabolism in gallbladder cancer cells." (PMID 38184562, 2024). "Recent studies have shown that PVT1 modulates the expression of HK2 by competing with endogenous miR-143 in gallbladder cancer (GBC) cells, which could provide valuable insights into the potential therapeutic targets for GBC at the molecular level." (PMID 38383348, 2024). "However, silencing HK2 expression can suppress proliferation, migration, and invasion of gallbladder cancer cell lines due to significantly reduced glucose consumption and lactate production." (PMID 35265223, 2022). "PVT1 and HK2 act as a ceRNA of miR‐143, which could regulate aerobic glucose metabolism in gallbladder cancer cells, and promote cell proliferation and metastasis." (PMID 34196116, 2021). "Sun and colleagues reported that lncRNA plasmacytoma variant translocation 1 (PVT1) acts as an oncogenic lncRNA in gallbladder cancer (GBC) by sponging and repressing miR-143, allowing HK2 to be overexpressed." (PMID 33652661, 2021).
Sepsis (14 papers, 2022 to 2025). Sepsis is defined as life-threatening organ dysfunction caused by a dysregulated host response to infection. "EGCG reduces EGFR and suppresses HIF-1α, HK2, PKM2, and iNOS expression, thereby attenuating sepsis-associated acute lung injury." (PMID 41322289, 2025). "In macrophages, ATF4 has been identified as a key glycolytic activator that contributes to the inflammatory response in sepsis by binding to the promoter region of Hk2." (PMID 39870616, 2025). "Genetic silencing or pharmacological inhibition of HK2 was found to be linked to the modulation of NLRP3 activation and lipid droplet aggregation in microglial cells of sepsis." (PMID 40086696, 2025). "We provide evidence to support that KLF14 can inhibit glycolysis in macrophages by suppressing HK2 transcription during sepsis." (PMID 34983946, 2022). "The glycolysis-encoding genes HK2 (hexokinase-2), HK3 (hexokinase-3), LDHA, and PKM (pyruvate kinase M) in the PMNs of patients with sepsis were significantly altered compared to those in the PMNs of healthy volunteers." (PMID 35090526, 2022). "Hexokinase 2 (HK2), an essential rate-limiting enzyme in glycolysis, was significantly up-regulated in PBMCs, underscoring its pivotal role in macrophage metabolic reprogramming during sepsis." (PMID 40171016, 2025). "Notably, inhibition of HK2 has been reported to suppress sepsis shock in mouse model, indicating an enhanced role of Hk2 in inflammatory responses." (PMID 41162494, 2025). "Our findings suggest that HK2 modulates ISGylation of ACSL4 in sepsis-induced microglial cells, indicating that therapeutic targeting of HK2 may constitute a promising strategy for SAE." (PMID 40086696, 2025). "Considering that HK2 and STING expressing macrophages are abundant in sepsis and are associated with drastic inflammation, we developed a novel immunomodulating agent referred to as LDO, which links glycolysis inhibitor LND with STING inhibitor 4-OI to achieve the dual inhibition of HK2 and STING." (PMID 40171016, 2025). "However, the molecular mechanisms governing HK2 dissociation from mitochondria in microglia during sepsis remain unknown." (PMID 40500776, 2025). "Finally, even though HK2 has not been assigned any prognostic value in sepsis, the enzyme has been significantly associated with mortality in several types of cancer." (PMID 37367740, 2023). "Our study underscores the pivotal roles of HK2 and STING in orchestrating the inflammatory response in sepsis and provides effective guidance for sepsis treatment." (PMID 40171016, 2025). "In conclusion, this study elucidates the central roles of HK2 and STING in metabolic reprogramming during sepsis therapy." (PMID 40171016, 2025). "Under hypoxic conditions in sepsis, HIF-1α acts as a key upstream molecule in glycolysis, promoting the expression of key glycolytic enzymes such as GLUT1, HK2, and PFKFB3." (PMID 39712019, 2024). "Mechanistically, by robustly attenuating STING signaling cascades and HK2-driven glycolysis, LDO actively down-regulates macrophage chemokine signaling pathways, especially CCL2, thus opening new avenues for targeted interventions in sepsis management." (PMID 40171016, 2025). "Drugs that target glycolytic enzymes, such as hexokinase 2 (HK2) or lactate dehydrogenase A (LDHA), are being explored as cancer therapies and could also be tested in sepsis." (PMID 40563999, 2025). "In addition to HK2, HK3 has gained increasing recognition for its pivotal role in the development and prognosis of sepsis." (PMID 39712019, 2024). "The aim of this study was to investigate the gene expression profile of HIF1A, ISG15, HK2, LDHA, HMOX1, EPO, and VEGFA under the setting of sepsis and septic shock, and furthermore to evaluate whether any of these molecules has potential value as a prognostic factor." (PMID 37367740, 2023).
diffuse large B-cell lymphoma (13 papers, 2018 to 2025). "During metabolism, WTAP can stabilize the HK2 mRNA, which is associated with aerobic glycolysis and the Warburg effect in diffuse large B-cell lymphoma." (PMID 36207306, 2022). "Increased HK2 expression correlates with tumorigenesis in patients with diffuse large B-cell lymphoma (DLBCL)." (PMID 40284466, 2025). "Importantly, HK2—a key 3BP target—is a known metabolic driver in diffuse large B-cell lymphoma (DLBCL) cell lines and patients." (PMID 40563683, 2025). "In diffuse large B cell lymphoma (DLBCL), WTAP increases the expression of its key target gene HK2 by elevating the level of HK2 m6A to promote DLBCL." (PMID 37297015, 2023). "Consistent with our results, high levels of HK2 expression are significantly associated with an aggressive phenotype in patients with primary diffuse large B-cell lymphoma (DLBCL), suggesting that HK2 level could be used to stratify DLBCL patients." (PMID 32709889, 2020).
head and neck squamous cell carcinoma (13 papers, 2016 to 2025). A squamous cell carcinoma that arises from any of the following anatomic sites: lip and oral cavity, nasal cavity, paranasal sinuses, pharynx, larynx, and salivary glands. "Therefore, the expression of miR-155, which is reported to target hexokinase 2 (HK2) through the direct inhibition of miR-143 in head and neck squamous cell carcinoma models, is implicated in clinical AI resistance." (PMID 30214383, 2018). "The regulation of HK2 by miRNA was further confirmed in head and neck squamous cell carcinoma (HNSCC)-derived cell lines." (PMID 36013278, 2022). "Hexokinase 2 (HK2) is upregulated in head and neck squamous cell carcinoma (HNSCC) and promotes survival of tumor cells by upregulating glycolysis." (PMID 32564010, 2020). "Using the starBase/ENCORI database, we also explored the potential correlation between ADAMTS9-AS2 and HK2 in head and neck squamous cell carcinoma (HNSCC) dataset and found an inverse correlation between ADAMTS9-AS2 and HK2 in HNSCC tumor samples." (PMID 40831535, 2025). "Taken together, HK2 seems to be a master promoting factor in controlling carcinogenesis in different cancers; to date, however, the role of HK2 in controlling head and neck squamous cell carcinoma (HNSCC) development was rarely focused." (PMID 32195170, 2020). "Glycolysis markers including glucose transporter 1 (GLUT1), monocarboxylate transporter 4 (MCT4), hexokinase 2 (HK2), pyruvate kinase M2 (PKM2) and glucose transporter 4 (GLUT4) play vital roles in head and neck squamous cell carcinoma (HNSCC)." (PMID 33653965, 2021).
nasopharyngeal carcinoma (13 papers, 2016 to 2024). A carcinoma arising from the nasopharyngeal epithelium. "The up-regulation of HK2 is responsible for EBV-increased glycolysis and correlates with the poor overall survival of nasopharyngeal carcinoma (NPC) that is caused by EBV infection in patients." (PMID 38257735, 2023). "Furthermore, the inhibition of hexokinase 2 by neoalbaconol induced selective cytotoxicity against nasopharyngeal carcinoma cell lines, and these effects were also observed in mouse models." (PMID 36771106, 2023). "Moreover, inhibition of hexokinase 2 (HK2) also provides a useful treatment modality for nasopharyngeal carcinoma." (PMID 33613518, 2020). "Epstein-Barr virus-encoded LMP1 significantly increases glycolysis in nasopharyngeal carcinoma (NPC) cells through up-regulation of hexokinase 2 (HK2), and then facilitates proliferation by blocking apoptosis." (PMID 32516328, 2020). "In a subcutaneous nasopharyngeal carcinoma model of nude mice, 3-BrPA-mediated inhibition of HK2, downstream of YAP/TAZ, also significantly inhibited the growth of nasopharyngeal carcinoma in mice." (PMID 33718214, 2021). "Knockdown of hexokinase 2 (HK2), the upregulation of which elevates aerobic glycolysis, effectively enhanced the sensitivity of latent membrane protein 1 (LMP1)-overexpressing nasopharyngeal carcinoma cells to irradiation." (PMID 27626688, 2016).
medulloblastoma (12 papers, 2012 to 2024). A malignant, invasive embryonal neoplasm arising from the cerebellum. "In medulloblastoma, Shh activation induces transcription of HK2 and PKM2, causing a robust increase in glycolysis." (PMID 36046646, 2022). "Loss of the HH pathway target hexokinase 2 results in disruption of cerebellar development and reduced tumor growth in the SmoA2 mouse medulloblastoma model." (PMID 26192445, 2015). "PPARG upregulates HK2 in medulloblastoma, and an agonist of PPAR signalling increases the rate of glycolysis in CD8+ cells." (PMID 35886000, 2022). "Second, a potential tumor-suppressive role for AMPK in SHH-driven medulloblastoma was also inferred by the fact that the increased survival observed upon Hk2 KO in a mouse model of medulloblastoma is accompanied by a gain of AMPK activity." (PMID 30360486, 2018).
colitis (11 papers, 2018 to 2025). Inflammation of the colon. "T cell specific-HK2 deficiency partially recovers intestinal inflammation in a spontaneous colitis model of IL-10 knockout (KO) mice, although HK2-deficient CD4+ T cells appear to have normal proliferation, viability, activation and differentiation in vitro." (PMID 37809060, 2023). "In a mouse model of colitis, HK2 deficiency conferred a limited degree of protection against inflammation." (PMID 30140438, 2018). "Elevated HK2 has been implicated in various cancers, including lung, breast, colorectal cancers, and glioblastoma, as well as inflammatory diseases, such as colitis and rheumatoid arthritis." (PMID 40643524, 2025). "We tested whether HK2 deficiency in T cells would impair T cell-mediated inflammation by using a mouse model of colitis driven by IL-10 deficiency." (PMID 30140438, 2018). "A metabolite generated from probiotic microbes, butyrate, was demonstrated to inhibit HK2 expression and safeguard wild-type mice from colitis." (PMID 41246320, 2025). "This study also demonstrated that colonic supplementation of the microbial metabolite butyrate ameliorated colitis in HK2-proficient littermate wildtype mice by suppressing HK2 expression." (PMID 39444028, 2024). "Hexokinases (HK) catalyze the first reaction of glycolysis and inhibition of epithelial HK2 protected from colitis in mice." (PMID 39444028, 2024). "Colonic expression of glycolysis-associated proteins such as HK2, lactate dehydrogenase A (LDHA), phosphate fructose kinase, and c-MYC are evidently enriched in inflamed tissues of DSS-induced colitis mouse model." (PMID 37809060, 2023). "Evidence from previous studies has shown that inhibition of HK2 protects from dextran sodium sulfate (DSS)-induced colitis by decreasing inflammation-induced epithelial cell death." (PMID 37497007, 2023). "While, HK2 is upregulated in the epithelium of patients with colitis." (PMID 38605718, 2024). "For instance, butyrate could exert a protective effect against colitis by downregulating Hexokinase 2 (HK2) in the intestinal epithelium via HDAC8." (PMID 36590401, 2022). "Similarly, in intestinal inflammation, elevated HK2 expression in epithelial cells induces cell death and mitochondrial dysfunction, while the gut microbial metabolite butyrate downregulates HK2, exerting protective effects against colitis." (PMID 40643524, 2025). "Hexokinase 2 (HK2) modulates mitochondrial metabolism, moderating inflammatory responses and cell death, thus safeguarding mice from DSS-induced colitis." (PMID 41425966, 2025). "Specifically, butyrate downregulates hexokinase-2 (HK2), which is upregulated in inflammation, via histone deacetylase 8 (HDAC8), thus alleviating colitis." (PMID 35050167, 2022). "A probiotic microbe-derived metabolite, butyrate, repressed the expression of HK2 and protected wild-type, but not mutant, mice from colitis." (PMID 38605718, 2024). "In a recent study, HK2 was identified as upregulated under inflammatory conditions in mice and humans irrespective of disease subtype (CD, UC, or non-IBD colitis) and suppressing HK2 expression even protected from experimental colitis placing HK2 as a potential disease marker." (PMID 39444028, 2024). "Finally, the correlation between NOR-mediated activation of AhR, repression of glycolysis, regulation of NAD+/SIRT1/SUV39H1/H3K9me3 signals, induction of Treg cells, and remission of colitis was confirmed in mice with DSS-induced colitis by using CH223191 and HK2 plasmid." (PMID 29449535, 2018). "The correlation between activation of AhR, repression of glycolysis, regulation of NAD+/SIRT1/SUV39H1/H3K9me3 signals, induction of Treg cells, and eventual anti-colitis effect of NOR were validated by using CH223191 and HK2 plasmid." (PMID 29449535, 2018).
laryngeal squamous cell carcinoma (11 papers, 2015 to 2024). A squamous cell carcinoma that arises from the larynx. "In laryngeal squamous cell carcinoma cells, ectopic expression of miR-125b-5p blocked glucose consumption by targeting hexokinase-2." (PMID 34884487, 2021). "It has been shown that miR-125b-5p exerts tumor suppressive role in laryngeal squamous cell carcinoma through repressing hexokinase-2 and glycolysis." (PMID 32201519, 2020). "In addition, miR‐125b targeted to HK2 and suppressed glycolysis in laryngeal squamous cell carcinoma." (PMID 34664737, 2021). "While the clinical applicability of these findings is yet to be determined, one study suggested miR-125a as a promising molecular target for laryngeal squamous cell carcinoma (LSCC) on the basis that miR-125a suppresses LSCC progression through targeting of HK2 both in vitro and in vivo analysis." (PMID 35145424, 2021). "Moreover, decreasing of HK2 expression in laryngeal squamous cell carcinoma (LSCC) reduced proliferation and cell viability by increasing G0-G1 ratio and apoptosis." (PMID 26017754, 2015).
leukemia (11 papers, 2013 to 2023). A malignant (clonal) hematologic disorder, involving hematopoietic stem cells and characterized by the presence of primitive or atypical myeloid or lymphoid cells in the bone marrow and the blood. "We confirmed these findings in leukaemia cells; treatment with both leptomycin and selinexor increased the levels of nuclear HK2, demonstrating that the nuclear export of HK2 requires exportin 1 (XPO1, also known as CRM1)." (PMID 35668135, 2022). "In order to identify other potential metabolic targets for T-ALL beyond HK2 that would preferentially inhibit leukemia while sparing lymphocytes, we compared in vivo proliferating T cells and primary mouse T-ALL cells by RNA-seq." (PMID 30140438, 2018). "JQ1 is able to restrain the glycolysis of leukemia cell lines by downregulating the rate-limiting enzymes of glycolysis, hexokinase 2, pyruvate kinase M2 (PKM2), and lactate dehydrogenase A. This effect is also mediated by the inhibitory effect of JQ1 on c-Myc, which enhances glycolysis." (PMID 37686632, 2023). "HK2 is the most highly regulated enzyme in cancer and activated T-cells, which suggests that HK2 could be a promising target for cancer therapy of T-ALL leukemia." (PMID 32300553, 2020). "We also detected HK2, but not other metabolic enzymes, in the nucleus of NB4, OCI-AML2, U937 and TEX leukaemia cells by immunoblotting and confocal microscopy." (PMID 35668135, 2022).